SNRPD2 (small nuclear ribonucleoprotein D2 polypeptide)
Description:
Plays a role in pre-mRNA splicing as a core component of the spliceosomal U1, U2, U4 and U5 small nuclear ribonucleoproteins (snRNPs), the building blocks of the spliceosome. Component of both the pre-catalytic spliceosome B complex and activated spliceosome C complexes. As a component of the minor spliceosome, involved in the splicing of U12-type introns in pre-mRNAs.
Synonyms: Sm-D2; SNRPD1; SMD2
Tractability: Small molecule: a structure with a bound ligand is known. PROTAC: UniProt records ubiquitination sites on it; ubiquitination databases record sites on it; its protein half-life has been measured.
Gene: Protein-coding gene on chromosome 19 (45,687,460 to 45,692,569, reverse strand). Ensembl gene ENSG00000125743.
Subcellular location: Cytoplasm, cytosol; Nucleus
Subcellular location (Human Protein Atlas): Cytosol
Pathways (Reactome):
Metabolism of RNA: mRNA Polyadenylation; mRNA Splicing - Major Pathway; mRNA Splicing - Minor Pathway; snRNP Assembly
Disease: Dengue Virus-Host Interactions; SARS-CoV-2 modulates host translation machinery
Chromatin organization: CHD1 and CHD2 subfamily
Gene Ontology:
Molecular function: protein binding; RNA binding
Biological process: mRNA splicing, via spliceosome; spliceosomal snRNP assembly; 7-methylguanosine cap hypermethylation; negative regulation of mRNA splicing, via spliceosome; RNA splicing; spliceosomal complex assembly; spliceosomal tri-snRNP complex assembly; spliceosome conformational change to release U4 (or U4atac) and U1 (or U11); U2-type prespliceosome assembly
Cellular component: catalytic step 2 spliceosome; cytosol; extracellular exosome; methylosome; nucleus; pICln-Sm protein complex; post-mRNA release spliceosomal complex; post-spliceosomal complex; precatalytic spliceosome; SMN-Sm protein complex; spliceosomal complex; U1 snRNP; U11/U12 snRNP; U12-type catalytic step 2 spliceosome; U12-type precatalytic spliceosome; U12-type spliceosomal complex; U2-type catalytic step 1 spliceosome; U2-type catalytic step 2 spliceosome; U2-type precatalytic spliceosome; U2-type spliceosomal complex; U4 snRNP; U4/U6 x U5 tri-snRNP complex; nucleoplasm; small nuclear ribonucleoprotein complex; U2 snRNP; and 6 more
Genetic constraint (gnomAD): Loss-of-function variants: 1 observed, 11.99 expected, observed/expected ratio (o/e) 0.0834, 90% interval 0.029 to 0.4. The upper end of that interval is the gene's LOEUF score, 0.4, which puts it in group 1 of 6, group 1 being the genes least tolerant of losing a copy. Missense variants: 77 observed, 162.84 expected, observed/expected ratio (o/e) 0.47, 90% interval 0.39 to 0.57. Synonymous variants: 63 observed, 64.07 expected, observed/expected ratio (o/e) 0.98, 90% interval 0.8 to 1.21.
Homologues: Orthologues: chimpanzee SNRPD2 (100% identical), macaque SNRPD2 (100% identical), mouse Snrpd2 (100% identical), rabbit SNRPD2 (100% identical), pig SNRPD2 (99% identical), rat Snrpd2 (99% identical), tropical clawed frog snrpd2 (99% identical), zebrafish snrpd2 (99% identical), macaque SNRPD2 (98% identical), rat Snrpd2l (97% identical), guinea pig SNRPD2 (89% identical), Drosophila melanogaster SmD2 (88% identical), and 3 more.
Diseases named in the same sentence as SNRPD2 in open-access papers:
SNRPD2 is named in the same sentence as 33 diseases in open-access papers, as found by Europe PMC text mining. Sharing a sentence is not in itself a finding about the gene and the disease. The quoted sentences say what the papers report.
hepatocellular carcinoma (7 papers, 2022 to 2024). A malignant tumor that arises from hepatocytes. "Researchers have evaluated a prognostic signature with 13 key genes including SNRPD2 for hepatocellular carcinoma patients." (PMID 35725413, 2022). "SNRPD2 is found closely associated with several cancers, including triple-negative breast cancer (TNBC) and hepatocellular carcinoma." (PMID 35356432, 2022).
lung carcinoma (3 papers, 2022 to 2025). "The panel included eight lung cancer cell lines, six of which were tested with siRNA silencing SNRPD2 before, and 17 cell lines representing cancers originating from the skin, pancreas, esophagus, colon, breast, and prostate." (PMID 39684842, 2024). "Similarly, we identified several splicing proteins, such as SNRPD2, SNRPG, SNRPD3, HNRNPM, HNRNPH3, and SRSF10, in human breast and lung cancer TuNEPs but not in NETs." (PMID 40751052, 2025).
ovarian carcinoma (3 papers, 2021 to 2026). A malignant neoplasm originating from the surface ovarian epithelium. "SNRPD2 is highly expressed in ovarian cancer and associated with an unfavorable prognosis." (PMID 41560375, 2026). "The overexpression of SNRPD2 promotes, whereas its depletion inhibits, the growth and migration of ovarian cancer cells." (PMID 41560375, 2026). "Aberrant expression or functional alterations of SNRPD2 in ovarian cancer may lead to splicing errors, affecting gene expression regulation in tumor cells." (PMID 38166541, 2024). "Moreover, SNRPD2 and AQR knockdown inhibited proliferation in breast, pancreatic and ovarian cancer cell lines." (PMID 33648524, 2021).
Alzheimer disease (2 papers, 2022). A progressive, neurodegenerative disease characterized by loss of function and death of nerve cells in several areas of the brain leading to loss of cognitive function such as memory and language. "Interestingly, SNRPD2 and SNRPG were not only major pathogenic genes of Alzheimer’s disease but also bridge genes." (PMID 35356432, 2022).
breast carcinoma (2 papers, 2021 to 2022). "Recent studies have found that SNRPD2 and SNRPD3, as RNA splicing factors, can inhibit the proliferation of breast cancer cells and laryngeal squamous carcinoma cells and participate in the study of cell cycle-related mechanisms during early fracture." (PMID 36389112, 2022).
glioma (2 papers, 2024 to 2025). A benign or malignant brain and spinal cord tumor that arises from glial cells (astrocytes, oligodendrocytes, ependymal cells). "Correlation analysis of SNRPD2 and SF3A3 expression against the expression of the 789 NJs across all glioma subtypes supported our hypothesis that decreased SNRPD2 and SF3A3 expression levels may contribute to greater NJ expression." (PMID 39972144, 2025).
lung adenocarcinoma (2 papers, 2024 to 2026). A carcinoma that arises from the lung and is characterized by the presence of malignant glandular epithelial cells. "The apparent opposite prognostic value of SNRPD2 expression in lung adenocarcinoma (LUAD) versus lung squamous cell carcinoma (LUSC), both subtypes of NSCLC, was striking." (PMID 39684842, 2024).
endometrial cancer (1 paper, 2026). Primary or metastatic malignant neoplasm involving the endometrium (mucous membrane that lines the endometrial cavity). "In vitro and in vivo functional assays demonstrate that silencing SNRPD2 suppresses endometrial cancer cell proliferation and metastasis." (PMID 41720762, 2026). "Here, we show that the Sm protein SNRPD2 is markedly upregulated in both fresh-frozen and formalin-fixed paraffin-embedded (FFPE) endometrial cancer specimens and that its overexpression correlates with poorer clinical outcomes." (PMID 41720762, 2026). "Thus, SNRPD2 maintains high DDX39B expression by preventing intron retention, and in turn, elevated DDX39B expression suppresses cryptic exon usage in CTSC to preserve CTSC expression, ultimately supporting malignant phenotypes of endometrial cancer." (PMID 41720762, 2026).
Immunodeficiency (1 paper, 2022). Failure of the immune system to protect the body adequately from infection, due to the absence or insufficiency of some component process or substance. "In the present study, we found that the SNRPD2 was associated with the immunodeficiency function, PD-L1 expression in the TCGA data set, and tumor-infiltrating immune cells in the TIMER." (PMID 35637857, 2022).
laryngeal squamous cell carcinoma (1 paper, 2022). A squamous cell carcinoma that arises from the larynx. "SNRPD2 and SNRPF are the core proteins related to below-background radiation, and further affect the proliferation of well-differentiated laryngeal squamous cell carcinoma cells." (PMID 36371223, 2022).
melanoma (1 paper, 2024). A malignant, usually aggressive tumor composed of atypical, neoplastic melanocytes. "In contrast, Mel 41 cells that were presumably not melanoma cells were insensitive to SNRPD2 silencing." (PMID 39684842, 2024). "In all non-malignant cell cultures except HUVECs, endogenous SNRPD2 expression was approximately 3-fold lower than that measured in the melanoma cultures." (PMID 39684842, 2024). "We found that SNRPD2 is overexpressed in most human solid tumors and that silencing it is lethal for cancer cells of many tissue origins including short-term cultured patient-derived melanoma cells, but not for non-malignant cells including cancer-associated fibroblasts." (PMID 39684842, 2024).
metastatic melanoma (1 paper, 2024). A melanoma that has spread from its primary site to another anatomic site. "Therefore, we examined the killing effect of silencing SNRPD2 in patient-derived metastatic melanoma cell cultures." (PMID 39684842, 2024).
uveal melanoma (1 paper, 2024). A melanoma derived from melanocytes of the uveal tract. "In particular, in uveal melanoma, high SNRPD2 expression appeared to be a very strong risk factor." (PMID 39684842, 2024).
tumor (11 papers, 2011 to 2026). "The result demonstrated that the SNRPD2 was associated with the tumor-infiltrating immune cells (all P < 0.05), and EIF4A3 was associated with the B cells, CD8+ T cells, neutrophil, and dendritic cells (P < 0.05)." (PMID 35637857, 2022). "Specifically, antisense oligonucleotides (ASOs) targeting SNRPD2 markedly reduced tumor growth in a patient-derived xenograft (PDX) model." (PMID 41720762, 2026). "Within this network, SNRPD2 was identified as a critical hub gene, and its overexpression was strongly correlated with advanced tumor grade, stage, and reduced overall survival (p < 0.001)." (PMID 41938511, 2026). "Based on the available data from the HPA database, we observed the high expression of SNRPD2 in tumor tissues compared with normal liver tissue." (PMID 34238242, 2021). "Our results demonstrated that SNRPD2 knockdown strongly reduced the tumor growth rate." (PMID 38890388, 2024). "Furthermore, we could correlate SNRPD2 expression to the responses of cancer cells to several FDA-approved anti-tumor drugs, especially to drugs inhibiting the cell cycle." (PMID 39684842, 2024). "Interestingly, in our analysis correlating SNRPD2 expression to anti-tumor drug sensitivity on a large panel of human cancer cell lines, we observed that cancer cells that were sensitive to treatment with several FDA-approved targeted drugs expressed higher SNRPD2 levels than resistant cancer cells." (PMID 39684842, 2024).
cancer (10 papers, 2021 to 2025). A tumor composed of atypical neoplastic, often pleomorphic cells that invade other tissues. "We show that SNRPD2 is overexpressed in almost all cancers and that this is associated with poor prognoses in several cancers." (PMID 39684842, 2024). "A pan-cancer analysis including 26 solid tumor types revealed that the SmD2-encoding SNRPD2 gene was overexpressed in almost all cancers." (PMID 39684842, 2024). "In several cancers, high SNRPD2 expression was associated with a poor prognosis." (PMID 39684842, 2024). "This demonstrated that SNRPD2 was generally overexpressed in tumors, was a putative prognostic biomarker in several cancers, and was associated with the activation of multiple gene sets that are considered hallmarks of oncogenesis and cancer progression." (PMID 39684842, 2024). "Our studies demonstrate broad cancer-selective vulnerability to the loss of SNRPD2 expression." (PMID 39684842, 2024). "To obtain some insight in the biological processes that are associated with the vulnerability of cancer cells to the loss of SNRPD2 expression, we performed a gene enrichment analysis for functionally related genes with similar essentiality profiles in cancer cells as SNRPD2." (PMID 39684842, 2024). "This notion was further supported by correlations found between SNRPD2 expression and sensitivity to several anti-cancer drugs targeting mitosis and protein degradation." (PMID 39684842, 2024). "As expected for an essential gene, all these cancer cell lines were found to be strongly dependent on an intact SNRPD2 gene (median Chronos dependency score = −2.10, i.e., considerably lower than for RNAi screens)." (PMID 39684842, 2024). "The identification of biological processes and pathways on which cells are similarly dependent as they are on the expression of SNRPD2 provided clues to begin understanding the cancer-selective lethality of silencing Sm genes." (PMID 39684842, 2024). "In this study, we performed an in silico pan-cancer analysis of SNRPD2 expression in patient samples, comparing gene expression to prognosis and to hallmarks of cancer." (PMID 39684842, 2024). "This suggests that cancer cells upregulate SNRPD2 expression because they depend on it and that this makes them more vulnerable to the inhibition of expression." (PMID 39684842, 2024). "The observation that the silencing of SNRPD2 or one of the other Sm genes—in contrast to most other spliceosome genes—is selectively lethal to cancer cells was thus surprising." (PMID 39684842, 2024). "To investigate this, we transduced a panel of 25 human cancer cell lines of various tissue origins with a lentiviral vector (LV) expressing a short hairpin targeting SNRPD2 (LV-shSNRPD2) or with an empty control LV (LV-EV)." (PMID 39684842, 2024). "SNRPD1, SNRPD3, and SNRPD2 have been identified as spliceosome-related proteins that have previously been crucial in the genesis of cancer." (PMID 36389112, 2022). "Proteins like SNRPG, SNRPD2, or even cancer-related are expected to be novel biomarkers to predict for patients with MCI who are more likely to progress to AD." (PMID 34461609, 2021). "This suggested that one outcome of high SNRPD2 expression in cancer cells could be downstream activation of EGFR/MEK pathways causing resistance to EGFR and MEK inhibitors." (PMID 39684842, 2024). "Overall, our study confirms the anticipated role for targeting SmD2 in cancer treatment and reveals non-canonical SmD2 functions beyond mRNA splicing that could contribute to the dependency of cancer cells to high SNRPD2 expression." (PMID 39684842, 2024). "Across the board, we observed that cancer cells—in contrast to non-malignant cells—are highly vulnerable to the loss of SNRPD2 expression." (PMID 39684842, 2024).
cancer (continued). "Our findings suggest that the dependency of cancer cells on high SNRPD2 expression might be explained by the dysregulation of mitosis and protein turnover in cancer cells, either via alternative splicing or through non-canonical functions of Sm proteins." (PMID 39684842, 2024). "In addition, we explored the dependency of a large panel of cancer cell lines on SNRPD2 expression by performing in silico analysis of public databases that collect cell viability data from gene knockdown and knockout screens." (PMID 39684842, 2024). "Detailed molecular mechanisms between SNRPD2 and cancer remain unknown." (PMID 35725413, 2022). "We observed a reduction in the LLPS of PABPN1 but not in its expression level in cancer cells and identified SNRPD2 and SNRNP70 as regulators of its phase separation." (PMID 40052530, 2025). "Conversely, cancer cells did not survive an approximately 3-fold reduction in SNRPD2 expression, i.e., to levels similar to those in untreated non-malignant cells." (PMID 39684842, 2024). "Hence, in contrast to cancer cells, all the tested non-malignant cells survived SNRPD2 gene silencing." (PMID 39684842, 2024). "However, there have been few study reporting the SNRPD2 and SNRPD3 functions in the cancer." (PMID 35637857, 2022).
SNRPD2 also shares sentences with these, for which no sentence is quoted: Sepsis (2 papers); triple-negative breast carcinoma (2); acute chest syndrome (1); adrenocortical carcinoma (1); anemia (1); autoimmune disease (1); breast invasive carcinoma (1); chromophobe cell renal carcinomas (1); coronary artery disease (1); diabetes (1); endotoxemia (1); kidney cancer (1); lung squamous cell carcinoma (1); mesothelioma (1); mild cognitive impairment (1); non-small cell lung carcinoma (1); renal cell carcinoma (1); renal papillary cell carcinoma (1).